SLC40A1 (solute carrier family 40 member 1)
Description:
Transports Fe(2+) from the inside of a cell to the outside of the cell, playing a key role for maintaining systemic iron homeostasis. Transports iron from intestinal, splenic, hepatic cells, macrophages and erythrocytes into the blood to provide iron to other tissues (By similarity). Controls therefore dietary iron uptake, iron recycling by macrophages and erythrocytes, and release of iron stores in hepatocytes (By similarity). When iron is in excess in serum, circulating HAMP/hepcidin levels increase resulting in a degradation of SLC40A1, thus limiting the iron efflux to plasma.
Synonyms: FPN; FPN1; IREG1; SLC11A3; MSTP079; MTP1; HFE4; MST079
Tractability: Small molecule: a structure with a bound ligand is known; a high-quality ligand is known. Antibody: UniProt places it where antibodies can reach, with high confidence; its Gene Ontology location is reachable by antibodies, with high confidence; UniProt predicts a signal peptide or a membrane-spanning region. PROTAC: UniProt records ubiquitination sites on it; ubiquitination databases record sites on it; a small molecule that binds it is known.
Target class: SLC40 iron transporter; Transporter; SLC superfamily of solute carriers; Electrochemical transporter
Gene: Protein-coding gene on chromosome 2 (189,560,538 to 189,583,758, reverse strand). Ensembl gene ENSG00000138449.
Subcellular location: Cell membrane; Basolateral cell membrane
Subcellular location (Human Protein Atlas): Cytosol; Plasma membrane; Nucleoplasm
Pathways (Reactome):
Disease: Defective CP causes aceruloplasminemia (ACERULOP); Defective SLC40A1 causes hemochromatosis 4 (HFE4) (duodenum); Defective SLC40A1 causes hemochromatosis 4 (HFE4) (macrophages)
Transport of small molecules: Iron uptake and transport; Metal ion SLC transporters
Gene Ontology:
Molecular function: ferrous iron transmembrane transporter activity; iron ion transmembrane transporter activity; peptide hormone binding; protein binding; identical protein binding
Biological process: intracellular iron ion homeostasis; iron ion transmembrane transport; iron ion export across plasma membrane; multicellular organismal-level iron ion homeostasis; transmembrane transport
Cellular component: basolateral plasma membrane; plasma membrane; cytoplasm; membrane; synaptic vesicle
Genetic constraint (gnomAD): Loss-of-function variants: 16 observed, 54.56 expected, observed/expected ratio (o/e) 0.29, 90% interval 0.2 to 0.44. The upper end of that interval is the gene's LOEUF score, 0.44, which puts it in group 1 of 6, group 1 being the genes least tolerant of losing a copy. Missense variants: 540 observed, 725.53 expected, observed/expected ratio (o/e) 0.74, 90% interval 0.69 to 0.8. Synonymous variants: 245 observed, 266.3 expected, observed/expected ratio (o/e) 0.92, 90% interval 0.83 to 1.02.
Homologues: Orthologues: chimpanzee SLC40A1 (100% identical), macaque SLC40A1 (99% identical), pig SLC40A1 (91% identical), rabbit SLC40A1 (91% identical), mouse Slc40a1 (91% identical), rat Slc40a1 (90% identical), guinea pig SLC40A1 (74% identical), tropical clawed frog slc40a1 (74% identical), zebrafish slc40a1 (68% identical), Caenorhabditis elegans fpn-1.2 (23% identical).
Diseases named in the same sentence as SLC40A1 in open-access papers:
SLC40A1 is named in the same sentence as 174 diseases in open-access papers, as found by Europe PMC text mining. Sharing a sentence is not in itself a finding about the gene and the disease. The quoted sentences say what the papers report.
iron deficiency (70 papers, 2005 to 2026). "Genetic alterations in the gene coding for transferrin (TF), transmembrane serine protease 6 (TMPRSS6), and solute carrier family 40 member 1 (SLC40A1) are the primary sources of genetic diversity leading to iron deficiency." (PMID 40081160, 2025). "The overexpression of SLC40A1 in cardiomyocytes resulted in iron deficiency, along with the induction of mitochondrial dysfunction, oxidative stress, and apoptosis." (PMID 38169607, 2024). "First, we observed that the overexpression of SLC40A1, specifically in cardiomyocytes, led to severe iron deficiency and induced mitochondrial dysfunction, oxidative stress, and apoptosis, subsequently resulting in the development of fatal HF in mice." (PMID 38169607, 2024). "The overexpression of SLC40A1 in the cardiomyocytes of adult mice resulted in significant iron deficiency, leading to mitochondrial dysfunction, oxidative stress, and apoptosis, subsequently resulting in the development of fatal HF." (PMID 38169607, 2024). "The global knockout of SLC40A1 in mice leads to embryonic lethality, while the selective knockout of SLC40A1 in postnatal intestine results in severe iron deficiency." (PMID 33117818, 2020). "Taken together, these data suggested that iron deficiency caused by overexpression of SLC40A1 in cardiomyocytes could induce myocardial mitochondrial dysfunction, oxidative stress, and apoptosis in mice." (PMID 38169607, 2024). "Also, SLC40A1 Q248H is associated with modest protection against anaemia and iron deficiency in African children." (PMID 32609760, 2020). "Mechanisms causing iron deficiency with inflammation are centered on increased hepatic hepcidin (encoded by HAMP) and decreased iron exporter ferroportin (FPN, also known as SLC40A1)." (PMID 38243847, 2024). "Current knowledge proposes iron deficiency or hypoxia to act via nuclear HIF-1/FIF-2a/HIF-b, triggering a transcriptional induction of Tfrc together with Hmox1, Slc11a2 (DMT1), Slc40a1 (FPN1), Epo, and Cp." (PMID 33023155, 2020). "For example, under the condition of iron deficiency, IRPs bind to the 3′ IREs of TFRC and SLC11A2 mRNAs and the 5′ IREs of SLC40A1 and FTH1/FTL mRNAs." (PMID 33117818, 2020). "In addition, the FPN gene Slc40a1 expression was downregulated in the hearts of IDA mice, as would be expected in iron deficiency, but the expression of the hepcidin gene Hamp was unaffected." (PMID 33553263, 2020).
breast cancer (46 papers, 2010 to 2025). A primary or metastatic malignant neoplasm involving the breast. "For instance, overexpression of SLC40A1 inhibits, while knockdown of SLC40A1 enhances, siramesine and lapatinib-induced ferroptosis by modulating iron efflux in breast cancer cells." (PMID 39534872, 2024). "When cultured with breast cancer cell lines, macrophages upregulate SLC40A1 and LCN2 to acquire an iron-releasing phenotype to support cancer proliferation." (PMID 34389031, 2021). "We observed over-expression of LIMCH1, a gene encoding zinc-binding protein, and also four genes encoding iron-binding proteins (LTF, SLC40A1, CYP4Z1 and CYP4Z2P) previously linked to breast cancer." (PMID 21209903, 2010). "Other selected genes, SLC40A1, ADAMTS15, THSD4, GREB1, and SLC44A4 have been reported to be related to breast cancer, and ZG16B, FDCSP, and SRARP have been associated with other types of tumors." (PMID 32795265, 2020). "TUBA1B+ TAMs, C1QC+ TAMs and VCAN+ TAMs were more prevalent in HER2+ breast cancer, whereas IL1B+ TAMs, SLC40A1+ TAMs and APOC1+ TAMs were more dominant in ER+ breast cancer, which illustrates the heterogeneity of TAM subtypes in various molecular subtypes of breast cancer." (PMID 39232806, 2024).
iron overload (45 papers, 2005 to 2026). "In this study, we report a pedigree with a heterozygous p.Y333H mutation in the Chinese Han population, analyze the clinical characteristics and describe the penetrance and expression of iron overload in SLC40A1-related HC with this mutation." (PMID 38886778, 2024). "In Chinese families, males over 30 years old with hemochromatosis due to SLC40A1 p.Y333H mutation exhibit severe iron overload phenotypes." (PMID 38886778, 2024). "We have established a web-based, manually curated database that gives a complete overview of the SLC40A1 variants which have been published in the medical literature and have been associated with mild to severe iron overload phenotypes." (PMID 40225168, 2023). "Mechanistically, heme-deficient primitive RBCs cause blood iron-overload via Slc40a1, and an HSPC iron sensor, Tfr1b, mediates excessive iron absorption." (PMID 37227070, 2023). "Another study on patients from the South African population identified significant associations between c.44–24G>C and c.663T>C SLC40A1 polymorphisms and iron overload." (PMID 36295822, 2022). "Aceruloplasminemia and Ferroportin disease due to loss-of-function mutation of SLC40A1, commonly show iron overload and low/normal TSAT." (PMID 34828384, 2021). "Since its discovery, we and others have identified a number of mutations in the gene encoding FPN (SLC40A1) associated with iron overload." (PMID 32301493, 2020). "In contrast, transfusional iron overload, alcoholic siderosis or iron overload caused by SLC40A1 mutations are typically characterized by iron laden macrophages." (PMID 30514216, 2018). "The A77D mutation and the Val162 deletion in the gene SLC40A1 would lead to hyperferritinaemia and reticuloendothelial iron overload." (PMID 25162662, 2014). "Although some studies suggest that FPN1 disease might be more frequent than believed, we have shown that only a minority (3.6%) of the patients with isolated hyperferritinemia and iron overload carried a mutation in SLC40A1." (PMID 36768886, 2023). "Also, it could potentially help in the diagnosis, prognosis or treatment of anemias, but also disorders of iron overload such as ferroportin disease or hemochromatosis type 4 resulting from the FPN1/SLC40A1 gene mutation." (PMID 39171088, 2024). "The results of Fisher’s exact test showed that the simultaneous presence of SLC40A1 and TMPRSS6 SNPs was strongly associated with serum ferritin concentration below 200 μg/L in this iron overload cohort (p < 0.00001; α error of 0.01)." (PMID 36295822, 2022). "The recovery of hepcidin effectiveness in mouse models of iron overload was only possible when Slc40a1 mRNA was essentially eliminated." (PMID 36066082, 2022). "Hyperferritinemia with iron overload includes hemochromatosis (HH) due to mutation in HFE, HJV, HAMP, TFR2 and SLC40A1 gain-of-function mutations, hereditary iron loading anemias, and hypo-transferrinemia that are characterized by high TSAT." (PMID 34828384, 2021). "In terms of genetics, different types of hereditary hemochromatosis are caused by mutations in the HFE, hepcidin (HAMP), hemojuvelin (HJV), ferroportin (SLC40)A1, and transferrin receptor 2 (TfR2) genes that correspond to genetic disorders of iron overload." (PMID 32635533, 2020). "An autosomal dominant form of iron overload is caused by mutations in the gene encoding the iron exporter and hepcidin receptor FPN (SLC40A1, solute carrier family 40 member 1)." (PMID 26182354, 2015). "It is worth mentioning that none of the heterozygous variants currently associated with SLC40A1-related iron overload phenotypes appear to result in a total absence of iron export." (PMID 40225168, 2023). "Interestingly, the allelic frequencies of the c.44–24G>C and c.663T>C SLC40A1 SNPs were found to be significantly higher in Italian blood donors with mild-to-moderate iron overload compared to the control group." (PMID 36295822, 2022).
iron overload (continued). "We also found cases with SLC40A1 HH had higher prevalence of cirrhosis and diabetes in this studies, which may be related to the severe iron overload and the late onset age of SLC40A1 HH." (PMID 34583728, 2021). "Moreover, the SLC40A1 gene may interact with the HFE, TFR2 genes, causing hyperferritinemia and an iron overload phenotype." (PMID 25162662, 2014). "The drugs LY2928057 and VIT2763, which inhibit SLC40A1/FPN1, have been investigated in phase I clinical studies for the treatment of anemia and iron overload." (PMID 39218897, 2024). "Other mutations, such as H63D in HFE or mutations in non-HFE genes like HAMP, HJV, TFR2, and SLC40A1 (FPN1), also contribute to iron overload but tend to have a variable clinical impact." (PMID 39323676, 2024). "This group includes disorders with or without iron overload caused by defects in genes involved in iron metabolism (FTL, SLC40A1, CP), as well as non-iron-related genetic disorders often associated with hyperferritinemia with normal TSAT." (PMID 36768886, 2023). "Of the 32 patients with primary iron overload (23 were males and 9 were females), non-HFE variants were detected in 31 (31/32, 97%), including 8 pathogenic variants in HJV, 7 pathogenic variants in SLC40A1, 8 likely pathogenic variants in SUGP2 and 5 likely pathogenic variants in DENND3 cases." (PMID 34583728, 2021).
anemia (40 papers, 2013 to 2025). A reduction in the number of red blood cells, the amount of hemoglobin, and/or the volume of packed red blood cells. "Hence, mice with macrophage-specific deletion of Slc40a1 that encodes for FPN are presented with mild anemia accompanied by splenic and hepatic iron accumulation, phenotypes that are exacerbated by hemolytic challenge or iron-deficient diet." (PMID 34573346, 2021). "The reduction of cellular iron export by the SLC40A1 protein is thought to be a component of an innate immune-driven strategy to prevent bloodstream pathogens from accessing iron, with anaemia as a side effect for the host." (PMID 40758728, 2025). "This is consistent with the work of Ganz (2020), who emphasized the importance of hepcidin-SLC40A1 regulation in anemia of inflammation." (PMID 39940407, 2025). "Anemia robustly increased expression of transferrin-a (tfa), solute carrier family 40 member 1 (slc40a1 or fpn1), and transferrin receptor 2 (tfr2), reflecting activation of an iron-mobilization response to meet erythropoietic demand (p < 0.05)." (PMID 41471763, 2025).
hemochromatosis (30 papers, 2005 to 2026). A disorder of iron metabolism characterized by a triad of HEMOSIDEROSIS; LIVER CIRRHOSIS; and DIABETES MELLITUS. "Liver biopsy and genetic testing confirmed a mutation in the SLC40A1 gene, encoding the ferroportin-1 protein, indicating a rare autosomal dominant form of hereditary hemochromatosis." (PMID 39171001, 2024). "Ferroportin exports iron from cells, and mutations in SLC40A1 lead to hemochromatosis (Mendelian Inheritance in Man (MIM) 606069)." (PMID 35606419, 2022). "In another study, the presence of at least one C allele of the c.44–24G>C SLC40A1 polymorphism was found to modulate the biochemical phenotype, specifically serum iron and transferrin saturation, in classical hemochromatosis patients." (PMID 36295822, 2022). "Hereditary hemochromatosis is caused by mutations in iron regulatory genes, including HAMP (hepcidin gene), HFE (hemochromatosis gene), TFRC (transferrin receptor), HJV (hemojuvelin), and SLC40A1 (ferroportin), and heterozygous mutations in BMP6 pro-peptide." (PMID 40871742, 2025). "Considering that in animal models of hereditary hemochromatosis (iron accumulation), in addition to Hfe gene knockout, there are several mouse models with Hamp, Hjv, and Slc40a1 (coded iron pump protein) knockout." (PMID 39159807, 2024). "Resistant to hepcidin, SLC40A1 mutations are rather associated with elevated plasma iron and parenchymal iron deposition, a condition that resembles HFE-related hemochromatosis and is associated with more clinical complications." (PMID 40225168, 2023). "Genes related to iron regulation, included Hfe, Slc40a1, Hmox1, Tfrc and Gdf15, all of which are directly involved in hemochromatosis and iron overload." (PMID 29257745, 2017). "An uncertainty of this study is that we may have excluded participants with "classic" SLC40A1 (ferroportin) hemochromatosis in whom SF but not TS is typically elevated." (PMID 35895739, 2022). "Whether this mutation affected the iron regulatory protein (IRP) interaction with the SLC40A1 IRE causing post-transcriptional ferroportin up-regulation and a hemochromatosis-like phenotype is not clear, as functional study was not performed and juvenile hemochromatosis genes were not sequenced." (PMID 34828384, 2021).
ferroportin disease (22 papers, 2010 to 2025). "Loss-of-function mutations of SLC40A1 cause HH type 4A (ferroportin disease), while gain-of-function mutations of SLC40A1 cause HH type 4B leading to hepcidin resistance." (PMID 40149659, 2025). "This situation will lead to ferroportin disease also known as hemochromatosis type 4 as a result of mutations occurring in the SLC40A1 gene associated with iron regulation, thereby causing dysregulation of hepcidin production." (PMID 40601756, 2025). "Mutations in SLC40A1 can cause autosomal dominant hemochromatosis, leading to iron overload conditions." (PMID 40078365, 2025). "SLC40A1 dysfunction causes ferroportin disease, and autosomal dominant iron overload disorder characterized by cellular iron retention, principally in reticuloendothelial cells, correlating with high serum ferritin and low to normal transferrin saturation." (PMID 40225168, 2023). "Loss-of-function variants in SLC40A1, instead, give rise to a distinct form of iron overload (ferroportin disease)." (PMID 36144223, 2022). "Type 4 hemochromatosis, which is affected by mutations in SLC40A1, a gene coding ferroportin-1, mutations, is known as ferroportin disease." (PMID 33673803, 2021). "Mutations in SLC40A1 in humans were first reported in 2001 and were found to cause autosomal dominant hemochromatosis (also known as ferroportin disease)." (PMID 33117818, 2020). "Mutations in the SLC40A1 gene lead to hemochromatosis type 4 (HC4), also called ferroportin disease." (PMID 33036384, 2020). "Three genes (COL3A1, COL5A2, and SLC40A1) have also been associated with autosomal dominant disorders (Ehlers-Danlos syndrome classical type, hemochromatosis type 4, and muscle hypertrophy)." (PMID 30911334, 2019). "The importance of Fpn1 for liver cell functions is evident from the clinical manifestations of ferroportin disease (type 4 hemochromatosis) which is caused by various mutations in the SLC40A1 (encoding FPN1) gene." (PMID 28251312, 2017). "Asparagine 144 may also be important for the function of SLC40A1, because two other disease-causing mutations, N144H and N144T, have also been identified in autosomal dominant hemochromatosis." (PMID 33117818, 2020). "Genetic variations in SLC40A1 can lead to an autosomal dominant form of hemochromatosis (ferroportin disease)." (PMID 40078365, 2025). "Ferroportin disease is hereditary hemochromatosis which is affected by SLC40A1, a gene coding ferroportin-1, and phenotypically classified into two forms (classical and nonclassical)." (PMID 33673803, 2021). "PolyPhen helps to score newly-identified, presumed SLC40A1 mutations; identification of a genetic variant in SLC40A1 is not sufficient to confirm ferroportin disease in patients with hyperferritinemia." (PMID 20691492, 2010).